EGFR (epidermal growth factor receptor)
Diseases named in the same sentence as EGFR in open-access papers (continued):
Sharing a sentence is not in itself a finding about the gene and the disease.
tumor (continued). "Furthermore, the tumor microenvironment (TME) of EGFR-mutated NSCLC, characterized by a low tumor mutation burden (TMB), impaired T cell activity, and high levels of immunosuppressive cytokines, further complicates treatment outcomes." (PMID 40733125, 2025). "In vivo, JWH-015 reduces tumor growth and inhibits EGFR/IGF-IR activation." (PMID 40275168, 2025). "Static magnetic field therapy operates through multiple mechanisms, including interference with oncogenic signaling pathways (such as EGFR), alteration of ionic environments and the cytoskeleton, and enhancing the tumor cells’ sensitivity to other treatments, all while avoiding additional toxicity." (PMID 40635706, 2025). "Although existing data on MVs in HNSCC are promising, a more detailed analysis of their molecular content may reveal novel biomarkers and help to elucidate mechanisms of tumor progression and therapeutic resistance, particularly during anti‐EGFR therapy." (PMID 40766966, 2025). "Notably, treatment with the PYCR1 inhibitor, PYCR1-IN-1, suppressed EGFR-driven 3D tumor spheroid formation, further demonstrating the functional relevance of PYCR1 in EGFR signaling." (PMID 41254241, 2025). "To further investigate this, we examined whether USP11 affects EGFR expression in vivo using xenograft tumor models." (PMID 41419456, 2025). "In the present case, the patient was young and had no significant medical history, and his tumor harbored an EGFR exon 19 deletion mutation." (PMID 41348429, 2025). "In some malignant tumours such as lung adenocarcinoma, RIT1 mutations appear to be mutually exclusive with mutations in currently known driver genes such as KRAS and EGFR, which suggests that RIT1 may be an independent oncogenic factor in some tumours." (PMID 39833023, 2025). "Therefore, while a higher IL-6 concentration increased the plasma concentration of osimertinib, IL-6 is expected to contribute to drug resistance and tumor progression during long-term EGFR-TKI therapy." (PMID 40156608, 2025). "Similarly, EVs carrying HER2 and EGFR provide valuable non-invasive tools for monitoring tumor status and tracking treatment response, making them essential for improving breast cancer detection and treatment personalization." (PMID 40530018, 2025). "Additionally, HER3 expression increases in response to anti-EGFR treatment, providing a potential escape mechanism for tumours that develop resistance, discussed in more detail in Section 3.3 below." (PMID 40940907, 2025). "Notably, the anti-EGFR antibody, Nimotuzumab, has been found to increase the expression of HLA Class I molecules on tumor cells." (PMID 39820491, 2025). "Although still by an unknown mechanism, miR-7 is abnormally downregulated in GBM, which is associated with tumor progression, likely due to its antiproliferative actions through the posttranscriptional inhibition of the PI3K and EGFR pathways." (PMID 40813676, 2025). "Additionally, SORT1 regulates EGFR internalization from the plasma membrane, thereby constraining proliferative signaling that drives tumor aggressiveness." (PMID 40781926, 2025). "The different distribution of PIK3CAmt according to primary tumour location and their relative resistance to EGFR-inhibitors, may partially explain survival differences according to primary tumour location." (PMID 40437037, 2025). "Over the past few years, novel GBM therapies have emerged, including gamma knife, proton beam, tumor-treating fields, and inhibitors targeting epidermal growth factor receptor (EGFR), vascular endothelial growth factor (VEGF), receptor tyrosine kinases (RTKs), and the PI3K pathway." (PMID 41011214, 2025). "Notably, IDH1 R132Q-expressing U87MG tumor xenografts had significantly increased transcripts of many integrins as described, as well as EGFR and MDM2 compared to R132H." (PMID 40188944, 2025).
tumor (continued). "Similarly, Lifirafenib and EGFR-IN-8, which target the epidermal growth factor receptor (EGFR), have demonstrated efficacy in inhibiting tumor growth and metastasis." (PMID 40573405, 2025). "Despite accepted benefit, tumor heterogeneity, the emergence of acquired resistance mechanisms, and individual immunologic profiles may diminish the efficacy of anti-EGFR therapies." (PMID 41590502, 2025). "For example, EGFR blockade may lead to compensatory upregulation of alternative pathways that facilitate tumor invasiveness and EMT." (PMID 41123660, 2025). "Initial studies have explored how EGFR mutant tumor cells create a suppressive TME." (PMID 40130724, 2025). "Given the cross-talk among VEGF signaling, EGFR pathways, and hypoxia responses, adding anti-angiogenic agents in selected, stratified populations may remodel the tumor microenvironment (TME) and potentiate both immunotherapy and chemotherapy." (PMID 41306958, 2025). "Since these trials were not designed to study the impact of ICIs in EGFR-mutant tumours, treatment efficacy in the EGFR-mutated group was studied by patient subgroup analysis." (PMID 40647497, 2025). "Dacomitinib, an EGFR inhibitor, reduces tumor viability and self-renewal in EGFR-amplified GBM, although its effectiveness is influenced by the PTEN status, Despite their initial promise, c-MET inhibitors such as onartuzumab and rilotumumab have failed to significantly improve survival outcomes." (PMID 40628732, 2025). "The mAb depatuximab not only targets the EGFRvIII, but is also able to bind to wild-type EGFR on neoplastic cells with EGFR amplification, even in the absence of EGFRvIII co-mutation, by binding to a tumor-specific, conformationally exposed epitope." (PMID 40361515, 2025). "We found that PDOs obtained from patients with a left-sided RAS/BRAF-WT tumor (n = 9) were more sensitive to EGFR inhibitor panitumumab, compared with PDOs obtained from patients with right-sided and/or RAS/BRAF-mutant tumors (n = 15; median-normalized GRAUC, 0.59 vs. 0.81; P = 0.012)." (PMID 40982295, 2025). "Upon administration, keynatinib binds to and inhibits EGFR T790M, a secondarily acquired resistance mutation, inhibits the tyrosine kinase activity of EGFR T790M, prevents EGFR T790M-mediated signaling, and leads to cell death in EGFR T790M-expressing tumor cells." (PMID 40723181, 2025). "EGFR mutations were more frequently occurred in never smokers (73.2% vs. former or current smokers 51.9%; P=0.0311) and patients with tumor diameter larger than 1.5cm (78.5% vs. tumor diameter less than 1.5cm 60.8%; P = 0.0247)." (PMID 40182027, 2025). "Thus, the addition of ICIs with EGFR inhibition leverages both direct tumor cell cytotoxicity and the activation of anti-tumor immunity, potentially aiding in overcoming resistance to EGFR inhibition alone." (PMID 40560045, 2025). "Interestingly, these tumour cell subpopulations all exhibit activation of the Wnt pathway, while showing lower activity in the EGFR, MAPK, NFκB, or TNF-α pathway." (PMID 39877290, 2025). "As a result, CMTM4 KO tumor cells have increased sensitivity to EGFR inhibitor." (PMID 39948411, 2025). "In cohort D of the CHRYSALIS-2 study, the combination therapy of amivantamab and lazertinib reported an ORR of 61% and mPFS of 12.2 months in patients with MET-positive (MET 3 or higher staining in ≥25% tumor cells) EGFR-mutant NSCLC progression on osimertinib." (PMID 40470164, 2025). "Moreover, many GBM driver mutations, such as loss of the tumour suppressor PTEN, or amplification of receptor tyrosine kinase-encoding genes, such as EGFR or platelet-derived growth factor receptor A (PDGFRA), can enhance PI3K−AKT−mTOR signalling." (PMID 40977288, 2025). "PKP2 accelerates tumor progression by promoting EGFR phosphorylation and activation." (PMID 40433361, 2025).
tumor (continued). "With this important caveat, we observed that these three genes exhibited significant downregulation in tumor cells from EGFR-mutant patients (L858R/Exon19del/Exon20ins) compared with non-mutant counterparts, though we cannot rule out that this expression pattern was influenced by the prior therapy." (PMID 41358202, 2025). "EGFR-targeted CAR-T cells recognize these epitopes to induce direct tumor cell lysis." (PMID 40904467, 2025). "In addition to DARPPN expression, intratumoral VEGFR2 expression was also correlated to EGFR tumor cell expression and mitotic count." (PMID 40969344, 2025). "Moreover, FASN inhibitors can block palmitoylation and plasma membrane- and mitochondria-associated EGFR activation and enhance cancer cell sensitivity to EGFR inhibitors by promoting EGFR ubiquitination, which further results in attenuating tumor growth." (PMID 41306968, 2025). "Engineered EVs equipped with surface proteins, such as anti-HER2 or anti-epidermal growth factor receptor (EGFR) antibodies, exhibit significantly improved tumor-targeting capabilities, positioning EVs as versatile platforms for addressing therapeutic resistance and advancing precision oncology." (PMID 40149276, 2025). "In cancer, for example, the expression of any one biomarker, such as HER2 or EGFR, can easily span a broad range between different tumor subtypes, or even within metastatic sites, making searching for broadly applicable biomarkers for diagnosis or treatment challenging." (PMID 40141854, 2025). "However, to validate the impact of CHIs in conjunction with EGFR-TKIs, the anti-tumor efficacy requires additional assessment over an extended observation period using PFS or overall survival." (PMID 41347160, 2025). "In addition to these advantages, EGFR is widely recognized as one of the primary clinical targets for tumor therapy." (PMID 40574864, 2025). "While further research is warranted to elucidate these mechanisms, our findings suggest that RKIP's tumor‐suppressive effects in EGFR‐mutant LUAD may be mediated through alternative pathways beyond BACH1‐EMT regulation." (PMID 40720248, 2025). "To further elucidate whether STARD4 regulates the progression and lenvatinib resistance of HCC via EGFR activation, we investigated the impact of EGFR inhibitor erlotinib on the tumor-promoting effect of STARD4 in HCC cells." (PMID 40831538, 2025). "Indeed, the patient from whom the LU-01-1377 tumor originated had a history of osimertinib treatment, and the LU-01-1377 xenograft tumor model exhibited resistance to EGFR-TKI inhibitors (erlotinib, afatinib, and osimertinib; data not shown)." (PMID 39995668, 2025). "Therefore, there is an urgent need for relevant research to comprehensively understand the relationship between EGFR and the tumor immunotherapy response in pan-cancer." (PMID 40574864, 2025). "This clearly indicated that the tumor accumulation of both tracers was EGFR-mediated." (PMID 41226646, 2025). "Importantly, EVs isolated from the blood, saliva, or other body fluids of patients with HNCs have been shown to carry tumor-specific molecular signatures, including PD-L1, EGFR, and non-coding RNAs, which correlate with disease stage and treatment response." (PMID 41410866, 2025). "In addition to being found in tumor cells, EGFR is also expressed in the endothelial cells of skin vessels." (PMID 39917172, 2025). "While the tumor growth delay could be partially explained by reduced RTK activity such as EGFR, the role of CD24a in immune modulation prompted us to investigate whether its knockout affects the TME." (PMID 40783744, 2025). "Moreover, acquired EGFR amplification is often accompanied by additional genetic alterations, potentially influencing tumor microenvironment and drug sensitivity." (PMID 39741120, 2025).
tumor (continued). "Preclinical models suggest that EGFR inhibition may enhance tumor immunogenicity, thereby improving responses to ICIs." (PMID 40677703, 2025). "Therefore, IONPs can be further engineered with specific targeting ligands that recognize overexpressed tumor markers, such as epidermal growth factor receptors (EGFR) or other cancer-specific antigens." (PMID 40887613, 2025). "In addition to CT or anti- EGFR therapies aimed at inhibiting tumor cell proliferation and survival, targets should be set to control the microenvironment which directs the cell’s mobility and provides a favorable environment for metastasis." (PMID 39857068, 2025). "The mitogen-activated protein kinase (MAPK)/ERK pathway, a key regulator of tumor proliferation, is initiated when receptor tyrosine kinases (RTKs), such as epidermal growth factor receptor (EGFR) or fibroblast growth factor receptor (FGFR), activate RAS GTPases." (PMID 40335986, 2025). "Additionally, we also examined the relationship between RiskScore and both Tumor Immune Microenvironment (TME) characteristics and EGFR mutation status." (PMID 41358202, 2025). "Research indicates that in the tumor microenvironment resistant to EGFR-TKIs, the expression of immune checkpoint molecules, such as PD-L1, may undergo significant alterations." (PMID 40003951, 2025). "We hypothesise that this balance represents a tumour-suppressive mechanism, in which junctional disassembly in dysregulated epithelial-to-mesenchymal transitions would shift this balance towards the EGFR:STAT signalling to promote apoptosis." (PMID 40690511, 2025). "The significant reduction in EGFr protein concentration following S. platensis treatment suggests that S. platensis may interfere with EGFr signaling, leading to decreased cell proliferation and potentially inhibiting tumor growth and progression." (PMID 41203700, 2025). "EGFRvIII, a tumor-specific variant of EGFR found in approximately 50% of GB cases and absent in normal tissues, offers high specificity and reduced off-target effects compared to targets such as HER2." (PMID 41304872, 2025). "Additionally, HIF2α attenuates EGFR endocytosis, sustaining EGFR-mediated signaling and contributing to tumor growth and progression." (PMID 40677703, 2025). "GCC2 knockdown reduced vesicle trafficking of EGFR to the nucleus and tumour proliferation." (PMID 40293576, 2025). "The pharmacokinetic behavior of these SNAP photoimmunoconjugates using a preclinical mouse model was investigated and demonstrated to specifically and optimally accumulate in EGFR‐expressing tumor xenografts 10 h after injection, with complete renal clearance achieved at 72h." (PMID 40970572, 2025). "Notably, EIF3B’s prognostic value in LSCC surpasses that of conventional markers like EGFR, which shows moderate correlation with tumor size but lacks specificity for aggressive subtypes." (PMID 40691141, 2025). "Acting downstream of EGFR and other RTKs, this pathway plays a central role in tumor progression." (PMID 41375018, 2025). "In addition, Cetuximab directs cytotoxic immune effector cells towards the EGFR overexpressed tumor, inhibits the cell cycle at the G1 phase, and induces apoptosis through the expression of the caspase-8 and Bcl-2 proteins." (PMID 40943615, 2025). "In the field of anticancer drug discovery, Zhang and co-workers developed a series of dual inhibitors targeting both the epidermal growth factor receptor (EGFR) and tumor-associated hCA IX by combining quinazoline-based derivatives with benzenesulfonamide moieties." (PMID 41011255, 2025). "Additionally, in CTCs, the expression of specific tumor cell markers, such as EGFR, MET tyrosine kinase receptor, and other markers associated with tumor aggressiveness, is analyzed." (PMID 39744583, 2025).
tumor (continued). "A deeper exploration of the intricate mechanisms governing the tumor microenvironment may offer innovative therapeutic strategies to overcome EGFR-TKI resistance as well as identify potential targets for future clinical treatments." (PMID 40003951, 2025). "The increased expression, mutation, and activation of the HER family members, in particular EGFR and HER2, have been reported in a wide range of human cancers and have been associated with tumour progression, resistance to therapy, and ultimately, a poorer prognosis." (PMID 40227788, 2025). "Their study revealed that EGFR co-localized with the inner nuclear envelope marker Lamin B1 in this tumor, suggesting that EGFR localization may serve as a predictive biomarker for a therapeutic response in IMPC." (PMID 40005948, 2025). "Nevertheless, AREG/EREG expression may offer further refinement in selecting candidates for anti-EGFR therapy both in distal and proximal tumor locations and should be evaluated together with genomic negative hyperselection." (PMID 41167084, 2025). "Moreover, the EGF-like domain of MUC3A enhances EGFR signaling, forming a feedforward loop that amplifies mucin-TF interactions during tumor progression." (PMID 40655139, 2025). "Additionally, PD-L1 upregulation induces autophagy through the MAPK pathway, promoting tumor progression and resistance to EGFR inhibitors." (PMID 39859304, 2025). "A similar experiment on co-localization of EGF-QDs with markers of the endocytic pathway in the control and under deacidification conditions on A549 tumor cells, which express a high number of EGFR, demonstrated the variability of endocytosis dynamics in tumor models (confocal images not provided)." (PMID 41155514, 2025). "The correlation between highly mutated tumour‐driver genes, such as PTEN (33%) and EGFR (24%), and GBM patient prognosis remains unclear." (PMID 41292185, 2025). "A drug delivery system by an anti-EGFR nanobody (7D12-9G8) for EGFR+ tumor cells has been reported." (PMID 39940647, 2025). "Additionally, tumor modulation strategies allow for the co-targeting of alternative pathways that contribute to resistance against EGFR inhibitors." (PMID 40002883, 2025). "Downregulates EGFR, inhibiting cell proliferation and tumor growth." (PMID 41409896, 2025). "PIK3CA mutations and PTEN loss activate the PI3K/AKT pathway, promoting tumor survival through mechanisms independent of EGFR." (PMID 40940901, 2025). "In a preclinical study, the combination of JHU083 with an EGFR peptide vaccine (EVax) in homozygous EGFR‐mutant mice leads to enhanced tumor infiltration of CD8+ T cells and CD4+ Th1 cells with an increasing oxidative metabolism and improves tumor suppression compared with EVax monotherapy." (PMID 40959206, 2025). "This selective microstructural disruption highlights the potential impact of EGFR-driven tumor biology on eloquent language networks, which may contribute to functional impairment and influence postoperative outcomes." (PMID 40941753, 2025). "Targetable mutation detection in tumor tissue using next-generation sequencing (NGS) by the GeneseeqPrimeTM panel (Nanjing Geneseeq Technology Inc., Nanjing, China) revealed EGFR exon 18 p.G719S mutation and EGFR exon 20 p.S768I mutation." (PMID 40277759, 2025). "EGFR is trans-activated, which intensifies tumor cell migration and invasion." (PMID 41421797, 2025). "In addition to these examples, immunoliposomes designed with enhanced targeting using ligand targeting of tumor specific markers, like EGFR-DOX." (PMID 40688030, 2025). "HER2 has the ability to form heterodimers with the EGFR, which maintains active tumor signaling." (PMID 40002260, 2025).